PLK4 (polo like kinase 4)
Description:
Serine/threonine-protein kinase that plays a central role in centriole duplication. Able to trigger procentriole formation on the surface of the parental centriole cylinder, leading to the recruitment of centriole biogenesis proteins such as SASS6, CPAP, CCP110, CEP135 and gamma-tubulin. When overexpressed, it is able to induce centrosome amplification through the simultaneous generation of multiple procentrioles adjoining each parental centriole during S phase. Phosphorylates 'Ser-151' of FBXW5 during the G1/S transition, leading to inhibit FBXW5 ability to ubiquitinate SASS6. Its central role in centriole replication suggests a possible role in tumorigenesis, centrosome aberrations being frequently observed in tumors. Also involved in deuterosome-mediated centriole amplification in multiciliated that can generate more than 100 centrioles. Also involved in trophoblast differentiation by phosphorylating HAND1, leading to disrupt the interaction between HAND1 and MDFIC and activate HAND1. Phosphorylates CDC25C and CHEK2. Required for the recruitment of STIL to the centriole and for STIL-mediated centriole amplification. Phosphorylates CEP131 at 'Ser-78' and PCM1 at 'Ser-372' which is essential for proper organization and integrity of centriolar satellites.
Synonyms: SAK; STK18; MCCRP2
Tractability: Small molecule: a drug acting on it is in phase 2 or 3 trials; a structure with a bound ligand is known; a high-quality ligand is known; it belongs to a druggable protein family. PROTAC: it is named in the literature on targeted protein degradation; UniProt records ubiquitination sites on it; ubiquitination databases record sites on it; a small molecule that binds it is known.
Target class: Other protein kinase PLK family; Kinase; Enzyme; Protein Kinase; Other protein kinase group
Chemical probes: PD081019, PD081219, PD081281, PD081516, PD081621, PD081731, PD082031, PD082121, PD082220, PD082287, PD082329, PD082484, PD082536, PD083030, PD083080, PD083107, PD083129, PD083139, PD083293, PD083492, and 25 more
Gene: Protein-coding gene on chromosome 4 (127,880,890 to 127,899,224, forward strand). Ensembl gene ENSG00000142731.
Subcellular location: Cytoplasm, cytoskeleton, microtubule organizing center, centrosome, centriole; Nucleus, nucleolus; Cleavage furrow; Cytoplasm, cytoskeleton, microtubule organizing center, centrosome
Subcellular location (Human Protein Atlas): Centrosome; Cytosol
Pathways (Reactome):
Cell Cycle: AURKA Activation by TPX2; Loss of Nlp from mitotic centrosomes; Loss of proteins required for interphase microtubule organization from the centrosome; Recruitment of NuMA to mitotic centrosomes; Recruitment of mitotic centrosome proteins and complexes; Regulation of PLK1 Activity at G2/M Transition
Organelle biogenesis and maintenance: Anchoring of the basal body to the plasma membrane
Gene Ontology:
Molecular function: identical protein binding; protein binding; protein serine kinase activity; protein serine/threonine kinase activity; ATP binding; protein kinase activity
Biological process: centriole replication; cilium assembly; positive regulation of centriole replication; de novo centriole assembly involved in multi-ciliated epithelial cell differentiation; trophoblast giant cell differentiation; regulation of cell cycle process
Cellular component: centriole; centrosome; procentriole; procentriole replication complex; cleavage furrow; cytosol; deuterosome; nucleolus; nucleus; XY body
Genetic constraint (gnomAD): Loss-of-function variants: 19 observed, 45.06 expected, observed/expected ratio (o/e) 0.42, 90% interval 0.29 to 0.62. The upper end of that interval is the gene's LOEUF score, 0.62, which puts it in group 2 of 6, group 1 being the genes least tolerant of losing a copy. Missense variants: 629 observed, 708.11 expected, observed/expected ratio (o/e) 0.89, 90% interval 0.83 to 0.95. Synonymous variants: 232 observed, 238.07 expected, observed/expected ratio (o/e) 0.97, 90% interval 0.88 to 1.09.
Homologues: Orthologues: chimpanzee PLK4 (99% identical), macaque PLK4 (97% identical), dog PLK4 (89% identical), pig PLK4 (88% identical), rabbit PLK4 (87% identical), guinea pig PLK4 (83% identical), rat Plk4 (79% identical), mouse Plk4 (79% identical), tropical clawed frog plk4 (59% identical), zebrafish plk4 (51% identical), Drosophila melanogaster SAK (31% identical). Paralogues in human: PLK2 (18% identical), PLK3 (17% identical), PLK1 (16% identical), PLK5 (8% identical).
Diseases named in the same sentence as PLK4 in open-access papers:
PLK4 is named in the same sentence as 126 diseases in open-access papers, as found by Europe PMC text mining. Sharing a sentence is not in itself a finding about the gene and the disease. The quoted sentences say what the papers report.
breast carcinoma (33 papers, 2011 to 2026). "In TRIM37‐amplified tumours, such as breast cancer, PLK4 inhibition causes centrosomal dysfunction and mitotic abnormalities, resulting in cell death." (PMID 41537447, 2026). "SAS-6, a key partner of PLK4 in centriole duplication, is implicated alongside PLK4 in breast cancer." (PMID 41488365, 2025). "This manuscript discusses the role of PLK4 as a promising therapeutic target in breast cancer, one of the most common causes of morbidity and mortality in women." (PMID 41092110, 2025). "Based on several studies, PLK4 overexpression has been associated with poor relapse-free survival and resistance to trastuzumab and tamoxifen therapy, in breast cancer patients." (PMID 41488365, 2025). "YLT-11 is another oral PLK4 inhibitor, which inhibits growth of human breast cancer cell lines and induces apoptosis by causing dysregulated centriole duplication and mitotic defects." (PMID 41092110, 2025). "In breast cancer, PLK4 is associated with centrosome amplification, aneuploidy and chromosomal instability, promoting invasive phenotypes and resistance to cancer cell death." (PMID 41092110, 2025). "A study elucidated that PLK4 mRNA expression is linked with a higher incidence of lymph node metastasis and distant metastasis or surrounding recurrence in breast cancer." (PMID 38326803, 2024). "A more comprehensive investigation further demonstrates that PLK4 overexpression occurs in 26% of all breast cancer tumors, and this overexpression has been associated with a reduced survival rate among breast cancer patients." (PMID 38606093, 2024). "Taking one study as an example, high levels of PLK4 transcripts are linked with poor relapse-free survival in patients with breast cancer." (PMID 38326803, 2024). "PLK4 genetic mutations of unknown clinical significance in breast cancer samples have also been reported." (PMID 41092110, 2025). "PLK-4 deletion caused death of breast cancer cells and inhibited breast cancer xenograft growth." (PMID 30315225, 2018). "Hence, aberrations of PLK1 and PLK4 can cause centrosome-related errors, which in turn impact genomic stability and cell division accuracy and thereby play a vital role in cancer, including breast cancer." (PMID 38606093, 2024). "A recent study demonstrated that YLT-11 (a novel Plk4 inhibitor) treatment caused abnormal centriole numbers and defective mitosis in BC cells, especially for triple-negative breast cancer (TNBC) cells." (PMID 33777739, 2021). "In TRIM37‐amplified tumours (such as neuroblastoma and breast cancer), PLK4 inhibition induces centrosomal dysfunction and mitotic abnormalities, ultimately leading to cell death—a synthetic lethal effect." (PMID 41537447, 2026). "PLK4 participation in breast cancer pathogenesis also involves the regulation of other cancer mechanisms such as cell death pathways." (PMID 41092110, 2025). "PLK4 plays an important role in centrosome amplification in breast cancer by regulating the essential process of centriole duplication." (PMID 41092110, 2025). "While there is lack of studies in terms of the role of PLK4 in breast cancer, one study confirms a potentially important role of PLK4 in breast cancer." (PMID 41092110, 2025). "Breast cancer is a significant health concern for females, where PLK4 has been shown to be dysregulated." (PMID 41488365, 2025). "PLK4, through the induction of supernumerary centrosomes and centrosome amplification leads to an invasive breast cancer cell phenotype." (PMID 41092110, 2025). "Preclinical studies have shown that PLK4 inhibitors lead to decreased proliferation, growth and migration and increased breast cancer cell death." (PMID 41092110, 2025).
breast carcinoma (continued). "This functional interaction between PLK4 and Arp2 was observed in PLK4-driven breast cancer cell motility via regulating Arp2/3-mediated actin cytoskeletal rearrangement." (PMID 41488365, 2025). "It was shown that treatment of breast cancer cells that overexpressed 17q23/TRIM37 with PLK4 inhibitor hindered the mitotic spindle assembly and accelerated cell death." (PMID 41488365, 2025). "Existing PLK4 inhibitors show great promise in the treatment of breast cancer, with their oral availability constituting one of the major advantages." (PMID 41092110, 2025). "Since, PLK4 depletion leads to a substantial decrease of breast cancer cells’ invasiveness into surrounding tissues in vivo, it is plausible that these effects are modulated by PLK4’s regulation of EMT." (PMID 41092110, 2025). "It was demonstrated that centrosome amplification elicited by PLK4 increased the invasiveness of breast cancer." (PMID 41488365, 2025). "Overall, the evidence strongly points to PLK4 as an important etiopathogenic factor in breast cancer." (PMID 41092110, 2025). "Using Oncomine database analysis, PLK4 mRNA expression has been reported to be elevated in breast cancer patients’ tumors compared with healthy tissues." (PMID 41092110, 2025). "Silencing PLK4 in breast cancer cells prevents centriole duplication, induces cell death and results in a significant decrease in MDA-MB-468 TNBC tumor growth in xenograft models." (PMID 41092110, 2025). "Other new compounds targeting PLK4 have been shown to specifically lead to anticancer effects in TRIM37-amplified breast cancer models." (PMID 41092110, 2025). "Overall, this data points to the possibility that PLK4 can serve as a valuable biomarker and drug target in breast cancer." (PMID 41092110, 2025). "TRIM37 plays an important function in centrosome regulation and is commonly amplified in breast cancer.When PLK4 is inhibited by centrinone, cell division takes place without centrosome duplication, leading to delayed, acentrosomal spindle assembly." (PMID 41092110, 2025). "Inhibition of PLK4 activity or its downregulation in breast cancer leads to tumor suppressive effects, such as decreased cancer cell viability, proliferation, growth and invasion." (PMID 41092110, 2025). "Together with studies from other cancer types, these results strongly suggest that PLK4 is an important new target for enhancing the sensitivity of breast cancer cells to radiotherapy." (PMID 41092110, 2025). "Similar results were obtained in patient-derived organoids presenting PLK4 as a target of therapy in TRIM37-amplified cases of breast cancer." (PMID 41488365, 2025). "In breast cancer cells, it was observed that PLK4-dependent RhoA activation promoted cell migration and invasion." (PMID 41488365, 2025). "In various breast cancer models, PLK4 depletion suppresses invasion and induces an epithelial phenotype." (PMID 41092110, 2025). "Overall, this review highlights that PLK4 is a promising therapeutic target for breast cancer and precision oncology." (PMID 41092110, 2025). "PLK4 mRNA in breast cancer cell lines showed significantly higher levels relative to primary human mammary epithelial cells (HMEC)." (PMID 41092110, 2025). "Polo-like Kinase 4 (PLK4), a regulator of centriole duplication, was found to be a promising target for drug development in breast cancer." (PMID 38365710, 2024). "PLK4 is often aberrantly expressed in breast cancer, which can lead to abnormal centrosome duplication and aneuploidy, thereby inducing genomic instability and consequently contributing to breast cancer tumorigenesis and poor clinical prognosis." (PMID 38606093, 2024). "YLT-11 is another novel PLK4 inhibitor which has shown substantial antiproliferative and antitumor effects in breast cancer cells in vitro and in vivo respectively." (PMID 38606093, 2024). "PLK4 plays an important role in centrosome amplification in breast cancer, overseeing the essential process of centriole duplication." (PMID 38606093, 2024).
breast carcinoma (continued). "PLK4 inhibition is an emerging new strategy for cancer, including breast cancer, and has been extensively studied." (PMID 38365710, 2024). "The expression of PLK4 in breast cancer tissues has also been found to be overexpressed, which was associated with poor prognosis and aggressiveness." (PMID 36620611, 2022). "For example, PLK4 enhances the invasion and metastasis capabilities of breast cancer cells by regulating the actin cytoskeleton via the actin-related protein (ARP) 2/3 complex." (PMID 36620611, 2022). "Previous studies reported that PLK4 was overexpressed in various tumors, including breast cancer, lung cancer, neuroblastoma, colorectal cancer, malignant rhabdoid tumors, and prostate cancer." (PMID 34342940, 2021). "A previous study on breast cancer showed that elevated Plk4 transcript levels were strongly correlated with E2F overexpression." (PMID 33777739, 2021). "For example, increased PLK4 expression promoted invasion and metastasis in breast cancer and neuroblastoma, while PLK4 expression declined during hepatocarcinogenesis, which makes it presumably being a tumor suppressor gene." (PMID 34342940, 2021). "Elevated expression of PLK4 has been detected in several cancers, and was negatively correlated with chemosensitivity and prognosis of breast cancer and glioblastoma." (PMID 34162828, 2021). "In recent years, numerous studies have reported that PLK4 is hyperactivated in several kinds of human cancers, including breast cancer, colorectal cancer, and pancreatic cancer." (PMID 30337519, 2018). "Extensive studies in the past decade have demonstrated that PLK4 is dysregulated in human breast cancer as well as other cancers." (PMID 30337519, 2018). "To experimentally control centrosome amplification, we generated human breast cancer MDA-MB-231 cells that inducibly express PLK4 under a doxycycline-dependent promoter." (PMID 28474672, 2017). "Studies from another research group showed that both NEK2A and polo-like kinase 4 (PLk4) are highly expressed in Her2-positive breast cancer cells exhibiting trastuzumab resistance." (PMID 25705694, 2015). "CCNB1 mRNA expression has been reported to be significantly and positively correlated with mRNA expression levels of CENPE, AURKB, PLK1, and PLK4 in both breast tumors and breast cancer cell lines." (PMID 21445301, 2011). "Furthermore, PLK4 plays an important role in breast cancer progression, where it appears to provide the contextual control of cancer cell migration and motility and the mediation of cytokinesis." (PMID 41092110, 2025). "Preclinical evidence of antitumor activity of PLK4 inhibitors in non-breast cancer malignancies." (PMID 41092110, 2025). "Breast cancer cells have been reported to be dependent on PLK4 for survival." (PMID 41092110, 2025). "In addition, several other compounds with PLK4 inhibitory activity have been recently reported to show potent anticancer effects in breast cancer, ovarian cancer and leukemia models." (PMID 41092110, 2025). "PLK4 inhibition by CFI-400945 in breast cancer in vivo and in vitro TNBC models has been shown to augment and synergize the effects of radiation treatment, through mechanisms that potentially involve overamplification of centrioles and alterations in DNA damage response and cell cycle regulation." (PMID 41092110, 2025). "Expression of PLK4 mRNA has been reported to be upregulated in ∼87% of patients with breast cancer." (PMID 41092110, 2025).